METTL27 (methyltransferase like 27)
Synonyms: WBSCR27
Tractability: PROTAC: ubiquitination databases record sites on it.
Gene: Protein-coding gene on chromosome 7 (73,834,012 to 73,842,539, reverse strand). Ensembl gene ENSG00000165171.
Subcellular location (Human Protein Atlas): Cytosol; Mitochondria
Gene Ontology:
Molecular function: protein binding
Genetic constraint (gnomAD): Loss-of-function variants: 29 observed, 22.84 expected, observed/expected ratio (o/e) 1.27, 90% interval 0.94 to 1.72. The upper end of that interval is the gene's LOEUF score, 1.72, which puts it in group 6 of 6, group 1 being the genes least tolerant of losing a copy. Missense variants: 299 observed, 275.97 expected, observed/expected ratio (o/e) 1.08, 90% interval 0.99 to 1.19. Synonymous variants: 119 observed, 121.62 expected, observed/expected ratio (o/e) 0.98, 90% interval 0.84 to 1.14.
Homologues: Orthologues: chimpanzee METTL27 (94% identical), chimpanzee METTL27 (80% identical), dog METTL27 (78% identical), pig METTL27 (78% identical), rabbit METTL27 (76% identical), rat Mettl27 (67% identical), mouse Mettl27 (64% identical), tropical clawed frog mettl27 (45% identical), zebrafish mettl27 (38% identical), Caenorhabditis elegans K12D9.1 (12% identical), Caenorhabditis elegans R08F11.4 (12% identical), Caenorhabditis elegans rips-1 (12% identical), and 1 more. Paralogues in human: AS3MT (17% identical), TMT1A (16% identical), TMT1B (16% identical), COQ5 (15% identical).
Diseases named in the same sentence as METTL27 in open-access papers:
METTL27 is named in the same sentence as 6 diseases in open-access papers, as found by Europe PMC text mining. Sharing a sentence is not in itself a finding about the gene and the disease. The quoted sentences say what the papers report.
Williams-Beuren syndrome (2 papers, 2020 to 2025). "WBSCR27, also known as METTL27, is a gene located in a contiguous gene deletion region at chromosome 7q11.22-q11.23 considered to be causative for Williams-Beuren syndrome, a rare autosomal dominant ID syndrome that includes multi-system phenotypes and characteristic facies." (PMID 33282601, 2020).
prostate carcinoma (1 paper, 2023). A carcinoma that arises from epithelial cells of the prostate gland. "This would be consistent with the notion that methylation of JMJD2D could promote prostate cancer development through upregulation of CBLC and METTL27 as well as through downregulation of COL4A5, GLIS3, NPR1, OSR2, PLAGL1 and RSPO3." (PMID 38045004, 2023).
tumor (1 paper, 2021). "Notably, three METTLs (METTL1, METTL7B, METTL27) were over-expressed in at least three of 15 TCGA tumor types compared to normal samples." (PMID 34285249, 2021).
METTL27 also shares sentences with these, for which no sentence is quoted: cancer (2 papers); cryptorchidism (1); Obesity (1).